FAM170A (family with sequence similarity 170 member A)
Description:
Acts as a nuclear transcription factor that positively regulates the expression of heat shock genes. Binds to heat shock promoter elements (HSE). Necessary for normal sperm head morphology, efficient spermiation, and sperm progressive motility (By similarity). Plays a crucial role in sperm chromatin remodeling by promoting the nuclear translocation and deubiquitinating activity of USP7 on histone H2A and H2B variants (By similarity). This ensures the timely removal of core histones, proper expression and degradation of transition proteins, and efficient incorporation of protamines during spermiogenesis (By similarity).
Synonyms: ZNFD
Tractability: No criterion of Open Targets' tractability assessment is met for any kind of drug.
Gene: Protein-coding gene on chromosome 5 (119,629,558 to 119,635,822, forward strand). Ensembl gene ENSG00000164334.
Subcellular location: Nucleus
Gene Ontology:
Molecular function: DNA-binding transcription factor activity, RNA polymerase II-specific
Biological process: positive regulation of DNA-templated transcription; transcription by RNA polymerase II; chromatin remodeling; fertilization; flagellated sperm motility; positive regulation of protein deubiquitination; positive regulation of protein import into nucleus; spermatid development; regulation of transcription by RNA polymerase II
Cellular component: nucleus
Genetic constraint (gnomAD): Loss-of-function variants: 27 observed, 34.8 expected, observed/expected ratio (o/e) 0.78, 90% interval 0.57 to 1.07. The upper end of that interval is the gene's LOEUF score, 1.07, which puts it in group 4 of 6, group 1 being the genes least tolerant of losing a copy. Missense variants: 420 observed, 402.97 expected, observed/expected ratio (o/e) 1.04, 90% interval 0.96 to 1.13. Synonymous variants: 152 observed, 146.66 expected, observed/expected ratio (o/e) 1.04, 90% interval 0.91 to 1.19.
Homologues: Orthologues: chimpanzee FAM170A (99% identical), rabbit FAM170A (76% identical), pig FAM170A (75% identical), mouse Fam170a (72% identical), rat Fam170a (72% identical).
Diseases named in the same sentence as FAM170A in open-access papers:
FAM170A is named in the same sentence as 4 diseases in open-access papers, as found by Europe PMC text mining. Sharing a sentence is not in itself a finding about the gene and the disease. The quoted sentences say what the papers report.
male infertility (2 papers, 2020). The inability of the male to effect fertilization of an ovum after a specified period of unprotected intercourse. "This work provides the first described role of FAM170A in reproduction and has implications for improving human male infertility diagnoses." (PMID 32588889, 2020).
Usher syndrome (1 paper, 2017). A syndromic diseae characterized by the association of sensorineural deafness (usually congenital) with retinitis pigmentosa and progressive vision loss. "Mutations were found outside of the CDR, including APC (N = 4), FAM170A (N = 2) and GPR98 (N = 2), the latter previously found to be involved in germ line mutation in Usher syndrome." (PMID 28031539, 2017).
FAM170A also shares sentences with these, for which no sentence is quoted: anal atresia (1 paper); Tracheoesophageal fistula (1).